CD4 (CD4 molecule)
Diseases named in the same sentence as CD4 in open-access papers (continued):
Sharing a sentence is not in itself a finding about the gene and the disease.
influenza (continued). "Consistent with previous findings by other groups, we further elaborate that IL-18Rα expression on CD8 and CD4 T cells strongly correlates with disease severity and shows that these can be recapitulated in a mouse model of mild and severe influenza." (PMID 41285788, 2025). "In this study, we comprehensively examined the impact of adjuvants in promoting recruitment of HA-specific CD4+ T cells during the primary response to a recombinant protein-based licensed influenza vaccine." (PMID 38543915, 2024). "This is consistent with previous studies on various types of influenza vaccines showing that CD4+ T cells act alongside CD8+ T cells to contribute to the vaccine’s effectiveness." (PMID 39669563, 2024). "Recent evidence has indicated an important role for CD4+ T resident memory (TRM) cells in mediating protection from influenza infection in the lung." (PMID 39283916, 2024). "In our study, we found increased neutrophils and CD4+ T cells in the heart in response to influenza infection suggesting that there is cellular recruitment to control the virus." (PMID 38750107, 2024). "In the current study, we evaluated the ability of R-DOTAP to promote the elicitation of epitope-specific CD4+ T cells to a licensed recombinant protein-based influenza vaccine (Flublok) after a single vaccination." (PMID 38543915, 2024). "HI titres and the frequency of influenza specific CD4+ T cells were equal across strains for the three cohorts on all visits, increased until day 28 and decreased at day 180 to values higher than baseline." (PMID 39340066, 2024). "Advax-SMTM adjuvant appears to work via enhanced non-inflammatory recruitment of immune cells to the site of vaccination, leading to enhanced antigen presentation to influenza-specific B cells and CD4 and CD8 T cells." (PMID 38793706, 2024). "Most of these cells expressed CD69, a marker of lung CD4+ TRM following influenza infection, resulting in a 50-100-fold increase in CD4+ TRM following heterologous rechallenge of rGP- or LCMV-derived CD4+ memory T cells." (PMID 39283916, 2024). "Previous studies have shown that patients with severe influenza have reduced CD4+ T cells and reduced CD4+/CD8+." (PMID 39624480, 2024). "In another set of experiments, we compared the effect of mRNA-LNP and LNP to IFNα, or factors that induce inflammation or influenza infection, on the survival of adoptively transferred naïve CD4 T cells." (PMID 38390323, 2024). "While influenza-specific CD4 + T cells can orchestrate an effective immune response via interactions with both B cells and CD8 + T cells, they also demonstrate direct antiviral activity mediated via production of perforin and IFN-γ 42,46." (PMID 39030218, 2024). "Vaccination also induces the development of memory cells specific to influenza in both CD4 and CD8 T-cells." (PMID 38543861, 2024). "This suggests an important protective role of IFNγ‐secreting CD4+ T cells in influenza which warrants further investigation in humans." (PMID 38317404, 2024). "Our data indicate enhanced activation-induced-marker (AIM) expression on CD4+ T cells in influenza-vaccination (IV)-treated peripheral blood mononuclear cells (PBMCs) upon stimulation with spike-protein-peptide pools." (PMID 39066369, 2024). "Overall, we demonstrate that CyCMV vaccine vector-induced, influenza-specific CD4 + TEM protect MCM from an otherwise lethal HPAI infection." (PMID 39030218, 2024). "In particular, a recent cohort study using 965 samples confirmed that CD4+ T cells play an important role in influenza immunity and have cross-strain immunity, which is independent of HAI titers." (PMID 39772053, 2024). "Rather, the magnitude of the CyCMV-induced, influenza-specific CD4 + T cell response correlated to protection from HPAI-induced death." (PMID 39030218, 2024). "Subsequent statistically powered CyCMV/Flu vaccine-based HPAI challenge studies in MCM are required to determine the mechanism of protection mediated by influenza-specific CD4 + T cells." (PMID 39030218, 2024).
influenza (continued). "IL-15 has previously been identified to support the generation of superior, lung-resident antiviral CD4 + T cells with the ability to protect against lethal influenza infection in mice." (PMID 39030218, 2024). "We next sought to determine the impact of heterologous infection or immunization priming of CD4+ T cells on the establishment of lung-infiltrating memory CD4+ T cells following influenza infection." (PMID 39283916, 2024). "Memory CD4 T cells are required for long-lived immunity and are induced by vaccination strategies, including those against influenza." (PMID 39328415, 2024). "The number of influenza-specific CD4+ polypositive T cells, defined as CD4+ T cells producing at least two of the following immune markers: CD40L, IFNγ, IL-2, and TNFα, exhibited similar trends between cohorts at any visit for any vaccine strain." (PMID 39340066, 2024). "Circulating Tfh cells are a prominent CD4+ T cell subset identified during influenza infection and vaccination, providing help to memory B cells for antibody production." (PMID 38892370, 2024). "In this study, we now provide strong evidence that diverse epitope distribution and effector functions by CD4 T cells can be elicited by a licensed protein-based influenza vaccine when combined with the novel adjuvant R-DOTAP." (PMID 38543915, 2024). "Survival correlates with the magnitude of lung-resident influenza-specific CD4 + T cells prior to challenge." (PMID 39030218, 2024). "The influenza-specific CD4+T cells were primarily of memory phenotype (CD28+CD45RA− or CD28null), with a significantly higher frequency than the cit-TNC-specific cells (p<0.05 in both groups)." (PMID 39557489, 2024). "We also see this transition in an infection setting, with levels of Ki67 expression among influenza-specific CD4 T cells declining to low levels 28 days post infection (Jodie Chandler, Ben Seddon, unpublished)." (PMID 38948729, 2024). "Together, our data show that heterologous priming with rGP immunization or LCMV infection had induced enhanced expansion of CD4+ Tfh and Th1 cells compared to both primary influenza and secondary homologous influenza infection." (PMID 39283916, 2024). "Influenza infection primed a CD4 T cell response of greater magnitude as compared to the inactivated influenza vaccine after initial exposure." (PMID 36992412, 2023). "The mechanism behind the negative impact of pre-existing antibodies is thought to be related to pre-existing influenza-specific CD4+ T cells capable of inhibiting antigen presentation by dendritic cells and subsequently reducing CD4+ T cell help to B cells." (PMID 37063867, 2023). "T cells and B lymphoblasts activated by APCs migrate throughout the body via the circulatory system, such as Intranasal immunization of Matrix-M adjuvanted influenza vaccine can activate antigen-specific CD4+ and CD8+ T cells responses in spleen." (PMID 37020548, 2023). "We detected IL-17 in the sera of our patients with severe COVID-1911, and also in lung-infiltrating influenza antigen-specific CD4+ T cells in our experimental mouse model of severe influenza." (PMID 37270623, 2023). "To reveal the mechanism by which GlcNAc exerts anti-influenza effects, we analyzed the effects of GlcNAc treatment on immune cells, including NK cells, CD4+ T cells, and CD8+ T cells." (PMID 37953509, 2023). "CD4+ T cells have been shown to be indispensable to reduce the density of bacteria by immunization of mice with a whole-cell vaccine in a model of influenza induced pneumococcal otitis media." (PMID 37222516, 2023). "Here, we analyzed the potency of R-DOTAP in inducing epitope-specific cytokine producing CD4 T cells to a recombinant influenza antigen, using traditional squalene-based adjuvants as comparators." (PMID 36851752, 2023). "In human challenge models of influenza and RSV infection, enrichment of CD4+ and CD8+ TRM cells in the airways was associated with mitigated respiratory symptoms, viral control, and reduced disease severity." (PMID 37884506, 2023).
influenza (continued). "In research geared towards a universal influenza vaccine, there has been an increased focus on how CD4 and CD8 responses against conserved viral epitopes can confer heterosubtypic protection against influenza." (PMID 37445784, 2023). "Previous studies by our group identified three major CD4 T cell epitopes in HA-B following the influenza infection of B6 mice, offering a good opportunity to broadly assess CD4 T cell specificity and immunodominance." (PMID 36851752, 2023). "Specifically, the data would support that not only does initial exposure to influenza influence antigenic responses, but natural infection or vaccination with an inactivated antigen differentially primes influenza-specific CD4 T-cell responses." (PMID 36992412, 2023). "The limited diversity of the CD4 T-cell repertoire in aged individuals, probably a consequence of age-related thymic involution, has been found to contribute to the poor response to influenza vaccination in a mouse model." (PMID 36817479, 2023). "Given the variability of influenza HA, a viable approach to enhance humoral immunity would be to boost CD4 T cell immunity to conserved epitopes." (PMID 37711622, 2023). "The clearance of influenza infection depends on the cooperation of CD4+ helper T lymphocytes, CD8+ cytotoxic T lymphocytes, and antibody-producing B lymphocytes." (PMID 37424789, 2023). "We took the advantage of this new technology to analyze the characteristics of influenza haemagglutinin (HA)-specific CD4+ T clones in a published dataset of scRNA/TCR-seq from four healthy individuals with influenza vaccination." (PMID 36655976, 2023). "We observed an increase in proliferation of CD4 T cells in human blood cells after both influenza viral challenge and IFNγ stimulation, as marked by the upregulation of Ki-67, but no increase in proliferation was detected after stimulation of NHP blood cells." (PMID 36624212, 2023). "Those with lower nadir CD4+ T cell counts tended to have higher humoral responses to influenza HA and RSV but lower antibody responses to pneumococcus." (PMID 36805331, 2023). "In this context, the adoptive transfer of lung CD4+ TRM cells provides better protection against influenza infection than CD4+ circulating memory T cells." (PMID 37545498, 2023). "Using a preclinical mouse model, we have assessed an R-DOTAP nanoparticle adjuvant system for its ability to promote CD4 T cell responses to vaccination with recombinant influenza protein." (PMID 36851752, 2023). "It has already been demonstrated that multifunctional CD4+ T cells contribute to protection against influenza infections." (PMID 36986773, 2023). "This agrees with previously published data demonstrating that aged mice mount a delayed CD4 T cell response to influenza infection compared to young mice." (PMID 37852965, 2023). "A trend towards lower antigen-specific CD4+ T cell levels in participants treated with JAK inhibitors was also seen when we measured the influenza-specific (Agriflu) CD4+ T cell levels at the 2–6 week post dose 3 timepoint." (PMID 38129594, 2023). "While the goal of most Influenza vaccinations is to achieve sterilizing immunity through neutralizing antibody titers, there is a role for resident memory CD4 and CD8 T cell populations in rapidly controlling virus that has evaded neutralizing antibody." (PMID 36639569, 2023). "It is now well accepted that CD4 T cells can provide a multiplicity of functions that contribute to protective immunity to influenza." (PMID 36851752, 2023). "We have recently found that high levels of ATP guide the accumulation of influenza-specific CD4+ T cells in the lung parenchyma, determining the severity of the lung pathology (data not shown)." (PMID 37143525, 2023). "While these changes were observed in the subsets of flu-specific CD4 T-cells, the frequency of flu-specific CD4 T-cells were unaffected." (PMID 37396956, 2023).
influenza (continued). "CD4+ influenza-specific T cells also support specific CD8+ T cells while maintaining their cytolysis activity by producing IFNγ and perforin." (PMID 36986773, 2023). "In vivo, CRTAM-deficient mice show reduced protective immunity against influenza, due to a reduced migration of influenza-specific CD8+ CTLs and diminished cytotoxic function of CD4+ T cells." (PMID 36979144, 2023). "For the incidence of influenza and severe pneumonia in RCTs as well as the ratio of CD4+/CD8+ lymphocytes, the evidence quality was low." (PMID 38044944, 2023). "Our technique successfully expands low-frequency influenza-specific CD4+ T cells from healthy individuals." (PMID 38304104, 2023). "To address the question, we used inactivated H5N1 influenza vaccine as an immunogen and examined immune responses against HA protein by tracking the development of specific memory CD4 T cells and B cells in HLA-DR1 transgenic mice, with or without H2-O." (PMID 37908352, 2023). "The magnitude of an individual’s memory CD4+ T cell response is negatively correlated with the severity of symptoms and viral shedding after challenge with influenza strains." (PMID 37063867, 2023). "One was a proinsulin specific beta chain, found in CD4+ T cells in our study but reported to recognize influenza in a HLA-A*0201 restricted fashion (found in both McPAS and VDJDB) and CMV with a HLA-C*07:02 restriction." (PMID 37908349, 2023). "Those with lower current and nadir CD4 had generally higher humoral responses to EBV and CMV, while those with lower nadir CD4 had higher influenza but diminished pneumococcus responses." (PMID 36805331, 2023). "Following the transfer of antigen-primed T cells into influenza-infected mice, IL-2 neutralization greatly decreases CD4+ TRM cell formation, and a residual memory population is maintained independently of IL-2 signaling." (PMID 37545498, 2023). "The production of CD4+ TRM cells post influenza infection, was maintained, and remained long term in the lungs of mice." (PMID 36211412, 2022). "Of note, when assessed for CD4 expression, CD4− and CD4+ iNKT cells were present in equal proportions in influenza-infected lungs but only CD4− iNKT cells exhibited cytotoxicity towards inflammatory monocytes." (PMID 35313965, 2022). "This is in line with our observation where immunotypes 2 and 7 with low immune stability, higher regulatory pressure and potentially inflammaging driven remodulation showed lower CD38+ CD4+ T follicular cell increase 7 days after influenza vaccination." (PMID 36081314, 2022). "To determine if there were any changes in the production of IFN-γ by influenza-specific CD4 and CD8 T cells, we stimulated lymphocytes in the lung with corresponding influenza peptides and measured IFN-γ production." (PMID 36033397, 2022). "Aging and senescence impact CD4 T helper cell (Th) subset differentiation during influenza infection." (PMID 34962049, 2022). "Conversely, poorly immunogenic regions targeted by bnAbs in HIV and influenza overlap with clusters of dominant CD4 epitopes, potentially conferring an intrinsic disadvantage for bnAb-bearing B cells in germinal centers." (PMID 36016115, 2022). "Flagellin from Salmonella typhimurium has also shown promising results in influenza vaccine formulations with an increased number of IFN-y producing memory CD4+ T cells." (PMID 36077216, 2022). "In this study, we have used experimental infection of B6 mice with a commonly studied Victoria strain of influenza (B/Brisbane 60/2008) to develop a valuable experimental model system to analyze the CD4 T cell responses to infection." (PMID 35215193, 2022). "In parallel, peptides from influenza antigens, such as those in the HA protein, are presented to influenza-specific CD4+ T cells in peripheral lymph nodes following infection and/or vaccination." (PMID 36311717, 2022).
influenza (continued). "M1 and NP in MVA combined with the HA stem, PB1 and M2 from H5N1, H7N1, H9N2, and H1N1 subtypes were shown to protect against a wide range of influenza strains and induced specific antibodies and CD4+ and CD8+ T-cell responses." (PMID 35663997, 2022). "In young mice, CD4 T cells differentiate appropriately in response to influenza infection, generating T helper subsets that participate in the anti‐viral response." (PMID 34962049, 2022). "This is the first time that candidate influenza HLA-II epitopes have been directly observed in a fully human infection model capable of generating personalised CD4+ T cell epitopes." (PMID 35051231, 2022). "Depletion of Treg cells during primary influenza infection results in an increased effector CD4+ response, while depletion following clearance of the virus delays recovery and resolution of inflammation." (PMID 36159872, 2022). "Collectively, these data suggested that there was an increased memory cycling CD8+ and CD4+ T cells in severe patients during the acute phase of influenza infection." (PMID 36064355, 2022). "The differentiation of viral specific naïve CD4+ T cells into early and late B cell helper T cells and Tfh effectors, in the MedLNs, depends on proper education by migratory cDC2 subsets carrying influenza antigens into these LNs." (PMID 36895258, 2022). "Influenza-specific CD4+ TRM cells characterize as Th1-like TRM cells secreting IFN-γ and IL-2 and contribute to enhanced protection against influenza." (PMID 36032142, 2022). "During influenza infection, CD4 T cells differentiate into subsets such as Th1 to help clear the virus and Treg to control immunopathology." (PMID 34962049, 2022). "For CD4 T cells, intrinsic defects promote delayed adaptive immune responses and recovery from influenza infection, but adoptive transfer studies have also shown that extrinsic factors also contribute to poor T cell function in the lung." (PMID 35821836, 2022). "This work confirms that internal influenza proteins, particularly M1, are a rich source of CD4+ and CD8+ T cell epitopes." (PMID 35051231, 2022). "We also found that aged mice treated with D+Q exhibited a higher percentage of GATA3 expressing influenza NP‐specific CD4 T cells." (PMID 34962049, 2022). "These assays revealed, first, that influenza-specific CD4 T cells are detectable in all three tissues sampled: mLN, spleen, and respiratory tract, indicating dispersal into both secondary lymphoid tissue and recruitment into the tissue site of infection." (PMID 35215193, 2022). "Our results indicate that influenza specific lung tissue resident Treg and conventional CD4+ T cell populations display distinct kinetics in response to secondary influenza infection." (PMID 36159872, 2022). "A group of scientists also targeted influenza M2e to DCs by fusing M2e with anti-Clec9, while HA of influenza was infused with an artificial adjuvant vector cell targeting DCs to induce CD4+ T cells and CD4+ Tfh cells." (PMID 36003947, 2022). "Influenza-specific CD4+ T cells are an important cornerstone to protection by next-generation universal influenza vaccines." (PMID 35385318, 2022). "Compared with younger adults, the aged respond poorly to many current influenza vaccines due to declining CD4 and CD8 T cell responses as well as B cell responses." (PMID 36056604, 2022). "Our results demonstrate that senolytic drugs can impact CD4 T cells, most likely by modulating the microenvironment, which then can influence T cell differentiation during the response to influenza infection." (PMID 34962049, 2022). "Comparing the intranasal or injected influenza vaccines, we found that the route of administration and the type of vaccines (inactivated vaccine and live vaccine) also affect the production of CD4+ TRM cells." (PMID 36471700, 2022). "In conclusion, we describe a harmonized and qualified ICS assay, which permits quantitative evaluation of CD4+ T cell responses induced by influenza vaccines." (PMID 36341380, 2022).